CKAP4 (cytoskeleton associated protein 4)
Diseases named in the same sentence as CKAP4 in open-access papers (continued):
Sharing a sentence is not in itself a finding about the gene and the disease.
colorectal cancer (2 papers, 2024 to 2025). A primary or metastatic malignant neoplasm that affects the colon or rectum. "Moreover, a small molecule inhibitor which disrupts the interaction between AEBP1 and CKAP4 has been studied in colorectal cancer cells and mouse models." (PMID 41149482, 2025). "By integrating findings from esophageal, gastric, pancreatic, and colorectal cancers, this review provides a unique, comprehensive overview of CKAP4 in GI oncology, underscoring CKAP4′s potential to revolutionize GI cancer diagnosis and treatment and paving the way for future translational research." (PMID 41149482, 2025). "In colorectal cancer (CRC), CKAP4 seems to mediate proliferation and migration as well as induce angiogenesis." (PMID 41149482, 2025). "The interaction between DKK1 and CKAP4 activates the PI3K/AKT signaling pathway, promoting cancer cell proliferation and metastasis in various GI malignancies, including esophageal, gastric, pancreatic, and colorectal cancers." (PMID 41149482, 2025).
glioblastoma (2 papers, 2022 to 2025). The most malignant astrocytic tumor (WHO grade IV). "In the literature, miR-671-3p has also been shown to regulate particles in the progression of glioblastoma by its effect on CKAP4 (cytoskeleton-associated protein 4) and MMP-9 (matrix metallopeptidase 9)." (PMID 35456388, 2022).
liver diseases (2 papers, 2020 to 2025). "In our study, statistically significant cutoff values for DKK1 and mRNA CKAP4 variables were determined to distinguish kidney diseases from liver diseases (P < .001)." (PMID 40922300, 2025).
lung adenocarcinoma (2 papers, 2020 to 2025). A carcinoma that arises from the lung and is characterized by the presence of malignant glandular epithelial cells. "On the other side, the serum levels of CKAP4 were also of relationship with distant metastasis of lung adenocarcinoma patients." (PMID 33614703, 2020). "The positive rates of CKAP4 and DKK1in lung adenocarcinoma were 74.6 and 79.1%, respectively, and in squamous cell carcinoma were 74.6 and 73.8%, respectively." (PMID 33614703, 2020). "Kimura group analyzed the values of CKAP4 and its ligand DKK1 on prognosis in 67 cases of lung adenocarcinoma and 61 cases of squamous cell carcinoma specimens." (PMID 33614703, 2020).
meningioma (2 papers, 2020). A generally slow growing tumor attached to the dura mater. "Furthermore, we were also able to monitor transitions for proteins like NEK9 and CKAP4 which have been reported to be associated with meningioma pathobiology." (PMID 32974197, 2020). "It should be noted that EGFR, as an affinity protein of CKAP4, was also significantly overexpressed in meningioma." (PMID 33614703, 2020). "We earlier reported an elevation in the levels of AHNAK, Gelsolin, S100 family of proteins, and several other proteins like CKAP4 that were specific to particular grades of meningiomas." (PMID 32974197, 2020). "Another research confirmed that CKAP4 expression was significantly elevated in tissue samples from patients with meningioma." (PMID 33614703, 2020). "Butthe biological function of CKAP4 in meningioma is still unclear and needs further study." (PMID 33614703, 2020).
atrial fibrillation (1 paper, 2025). A disorder characterized by an electrocardiographic finding of a supraventricular arrhythmia characterized by the replacement of consistent P waves by rapid oscillations or fibrillatory waves that vary in size, shape and timing and are accompanied by an irregular ventricular response. "In the selection of feature genes for atrial fibrillation, LDHB, DPEP2, BCL11B, CKAP4, RORA, PFKFB2, and CXCR4 were identified as potentially important predictors, with the model error being lowest when the number of genes reached eleven." (PMID 41359645, 2025). "In the atrial fibrillation dataset, LDHB, PFKFB2, CKAP4, CXCR4, DPEP2, and RORA genes showed an upregulation trend, while only the CD81 gene was downregulated in the disease group." (PMID 41359645, 2025).
cholesteatoma (1 paper, 2015). A pathologic process characterized by the proliferation of keratinizing squamous epithelium resulting in the accumulation of keratin and cells in the middle ear and/or mastoid. "Cytoskeleton-associated protein 4 (CKAP4) primarily functions in skin development and maintenance, implying its presence in cholesteatoma-involved bone correlates with presence of invasive disease." (PMID 26608071, 2015).
Cognitive impairment (1 paper, 2025). Abnormal cognition is characterized by deficits in thinking, reasoning, or remembering. "Additionally, decreased CKAP4 may contribute to neuroinflammation, increased neuronal vulnerability, and impaired synaptic plasticity, all of which could exacerbate the neurological and cognitive impairments observed in DM1 patients." (PMID 41383381, 2025).
diabetes (1 paper, 2024). "Senescence proteins CKAP4 and PTX3 were shown to be capable of distinguishing AKI and CKD patients from a comorbid control cohort including patients with diabetes, CVD, and RA." (PMID 39404377, 2024).
diabetic kidney disease (1 paper, 2025). Progressive kidney disorder caused by vascular damage to the glomerular capillaries, in patients with diabetes mellitus. "CKAP4 is reduced in the glomeruli of diabetic kidney disease patients." (PMID 40493405, 2025).
endothelial dysfunction (1 paper, 2025). In vascular diseases, endothelial dysfunction is a systemic pathological state of the endothelium (the inner lining of blood vessels) and can be broadly defined as an imbalance between vasodilating and vasoconstricting substances produced by (or acting on) the endothelium. "These included genes such as CLNS1A, UGP2, RNF216, PHGDH, CKAP4, and IL6R, many of which are known to participate in inflammatory pathways, oxidative stress, and endothelial dysfunction." (PMID 41262879, 2025).
fibrosis (1 paper, 2021). the formation of excess fibrous connective tissue in an organ or tissue in a reparative or reactive process. "Quantitative PCR proved that CKAP4 was differentially expressed in two groups, and the expression was significantly down-regulated in the remodeling fibrosis group." (PMID 35004889, 2021).
focal segmental glomerulosclerosis (1 paper, 2025). A renal disorder characterized by sclerotic lesions in the glomeruli. "Moreover, HPODs exposed to hyperglycemia showed a significant decrease of CKAP4 expression at protein level, and a treatment with ADR, which is used as an injury model for focal segmental glomerulosclerosis, did not cause a reduction of CKAP4 in cultured HPODs." (PMID 40493405, 2025).
Hyperglycemia (1 paper, 2025). An increased concentration of glucose in the blood. "Hyperglycemia caused a reduction of CKAP4 of around 20%–30% when compared with its osmotic control and untreated cells." (PMID 40493405, 2025). "Taken together, these results demonstrate that patients with DKD have a decreased gene expression of CKAP4 and establish a direct connection between hyperglycemia and reduction of CKAP4 expression." (PMID 40493405, 2025).
intrahepatic cholangiocellular carcinoma (1 paper, 2020). "CKAP4 has been related to intrahepatic cholangiocellular carcinoma (ICC) prognosis." (PMID 33614703, 2020).
kidney (1 paper, 2025). "Evaluation of additional parameters, including histological examinations, inflammatory cytokine level assessments, and immune cell profiling in larger cohorts, may aid in further clarifying the potential role of DKK1 and CKAP4 in kidney transplant rejection." (PMID 40922300, 2025).
kidney transplant (1 paper, 2025). A surgical procedure in which one or both kidneys from a donor are implanted into a recipient. "Nevertheless, there remains insufficient information regarding how CKAP4 and DKK1 interact during kidney transplant rejection." (PMID 40922300, 2025).
leukemia (1 paper, 2024). A malignant (clonal) hematologic disorder, involving hematopoietic stem cells and characterized by the presence of primitive or atypical myeloid or lymphoid cells in the bone marrow and the blood. "Consistently, western blotting analysis showed that CKAP4 was overexpressed in a broad subset of solid tumor cell lines, but not in leukemia cell lines." (PMID 39528501, 2024).
liver cancer (1 paper, 2025). An epithelial or non-epithelial malignant neoplasm that arises from the liver. "This discrepancy underscores the complex and potentially context-dependent role of CKAP4 in cancer progression and highlights the necessity for further research to elucidate its precise function in GI cancer, and especially in liver cancer." (PMID 41149482, 2025).
lung disease (1 paper, 2024). "CKAP4 is well established as a biomarker of differing conditions, including playing a role in lung disease and in tumor formation and being upregulated in certain types of cancers." (PMID 39404377, 2024).
melanoma (1 paper, 2018). A malignant, usually aggressive tumor composed of atypical, neoplastic melanocytes. "A few genes located nearby the most significantly associated SNPs in this study have been described as involved in melanoma tumor biology (CKAP4, ID4, SATB1, and PLEKHA5), but not in melanoma susceptibility." (PMID 29963229, 2018).
mucinous adenocarcinoma (1 paper, 2019). An invasive adenocarcinoma composed of malignant glandular cells which contain intracytoplasmic mucin. "PAX8 and C-KIT were upregulated in most tumor types, while CKAP4 and DUSP1 were upregulated only in serous and mucinous adenocarcinoma." (PMID 31159852, 2019).
multiple myeloma (1 paper, 2023). "Another study reported that DKK-1 binds CKAP4 to activate NF-kB signaling and drug resistance in multiple myeloma." (PMID 38067123, 2023).
Myocardial fibrosis (1 paper, 2021). "Our results indicate that CKAP4 expression is downregulated in the enlarged myocardium caused by human valvular diseases, which may be associated with myocardial fibrosis." (PMID 35004889, 2021).
periodontitis (1 paper, 2026). An acute or chronic inflammatory process that affects the tissues that surround and support the teeth. "CKAP4 regulates OC apoptosis to maintain periodontal homeostasis and its downregulation in periodontitis promotes pathological bone resorption." (PMID 41969105, 2026).
prostate carcinoma (1 paper, 2023). A carcinoma that arises from epithelial cells of the prostate gland. "Some of these proteins with reduced expression after surgery are EMMPRIN, 60 kDa heat shock protein (HSP60), and glypican-1 (GPC1) for CRC, cytoskeleton-associated protein 4 (CKAP4) for PDAC, and prostate-specific membrane antigen (PSMA) for prostate cancer." (PMID 36831648, 2023).
renal fibrosis (1 paper, 2025). A final common manifestation of a wide variety of chronic kidney diseases characterized by glomerulosclerosis and tubulointerstitial fibrosis. "Ckap4 has a role in preserving endoplasmic reticulum sheets, is linked to the progression of CKD, and is a possible target for pharmacological interventions aimed at treating renal fibrosis." (PMID 40564035, 2025).
sarcopenia (1 paper, 2025). Progressive decline in muscle mass due to aging which results in decreased functional capacity of muscles. "DKK3, a myokine, regulates mitochondrial function and myotube structure via CKAP4 and may serve as a target for muscle atrophy prevention in conditions such as COPD-related sarcopenia or exercise-induced muscle wasting." (PMID 40870030, 2025).
Stroke (1 paper, 2023). Sudden impairment of blood flow to a part of the brain due to occlusion or rupture of an artery to the brain. "Higher relative concentrations of plasma CLEC4G, CKAP4, and IL-6 were associated with higher stroke severity, whereas LY75 and ITGA11 showed an inverse association." (PMID 37468969, 2023). "The second confirmed association with stroke severity is with CKAP4, although the earlier known associated score was also the NIHSS, the mRS represents again a new finding." (PMID 37468969, 2023). "The biomarkers CLEC4G, CKAP4, IL6, LY75 and ITGA11 were found to be significantly associated with stroke severity as measured by mRS and in case of IL6 and ITGA11 also by NIHSS." (PMID 37468969, 2023). "The present study confirmed the positive associations between stroke severity and IL6 and CKAP4, but also elucidated novel associations, namely between CLEC4G, LY75 and ITGA11, which enrich the present knowledge of blood biomarkers associated with stroke." (PMID 37468969, 2023). "The authors hypothesized that CKAP4 may be involved in the immune response following stroke and may serve as a potential therapeutic target." (PMID 37468969, 2023). "One study found that CKAP4 expression was increased in the infarcted area of rat brains after stroke, suggesting that CKAP4 may be involved in the inflammatory response and neuronal damage following stroke." (PMID 37468969, 2023).
cancer (45 papers, 2007 to 2025). A tumor composed of atypical neoplastic, often pleomorphic cells that invade other tissues. "Cytoskeleton-associated protein 4 (CKAP4) has garnered significant attention in cancer research due to its significant role in tumor progression, diagnosis, and therapy." (PMID 41149482, 2025). "The aim of this study was to evaluate CKAP4 expression in tumor cells and cancer-associated fibroblasts (CAFs) following radical cystectomy (RC) in patients with BCa." (PMID 40282454, 2025). "CKAP4 has also been identified as a receptor for Adipocyte enhancer-binding protein 1 (AEBP1) on cancer-associated fibroblasts (CAFs)." (PMID 41149482, 2025). "CKAP4 has been associated with various cancers and has attracted considerable attention in recent years." (PMID 40282454, 2025). "CKAP4 is potentially to be a robust molecular identification to study solid stress-associated cancer biology." (PMID 39528501, 2024). "Dickkopf1 (DKK1) is overexpressed in various cancers and promotes cancer cell proliferation by binding to cytoskeleton-associated protein 4 (CKAP4)." (PMID 34117362, 2021). "The aims of this study were to evaluate the expression levels of CKAP4 in tumor cells and cancer-associated fibroblasts (CAFs) using immunohistochemical analyses of archived RC specimens and to assess the impact of CKAP4 on the prognosis of patients who underwent RC for BCa." (PMID 40282454, 2025). "The analysis revealed that CKAP4 was connected to a higher risk of cancer recurrence, which means that CKAP4 could be a useful clinical tool to predict cancer recurrence after surgery." (PMID 40282454, 2025). "In addition, GOLPH3 (Golgi phosphoprotein 3) and CKAP4 (cytoskeleton-associated protein 4) are two proteins localized in the Golgi apparatus and upregulated in several types of cancer by enhancing the secretion of exosomal WNT3A." (PMID 37296620, 2023). "Furthermore, an anti-CKAP4 polyclonal antibody (pAb) can significantly reduce xenograft tumor volume and weight caused by these cancer cell lines, suggesting that CAKP4 represents a novel molecular target for cancer therapy." (PMID 33614703, 2020). "APF inhibits the proliferation of normal bladder epithelial cells and cancer cells in vitro, presumably by binding to its cellular receptor, cytoskeleton associated-protein 4 (CKAP4); however, the biophysical interaction of APF with CKAP4 has not been characterized previously." (PMID 28893174, 2017). "Release from cancer cells via exosomes as well as tumor expression levels play a significant role in the presence of CKAP4 in the serum of cancer patients." (PMID 41149482, 2025). "The median times to cancer death and recurrence for patients with positive CKAP4-1 were 39.3 and 28.8 months, respectively." (PMID 40282454, 2025). "First, CKAP4 facilitates cancer invasiveness by orchestrating a central-to-peripheral gradient of cell surface stiffness." (PMID 40282454, 2025). "As such, the mechanical properties of central-to-peripheral stiffness, lamellipodia formation, and exosomal CKAP4 significantly correlated with the invasiveness and metastasis of several cancers." (PMID 40282454, 2025). "The interaction between DKK1 and CKAP4 promotes metastasis by enhancing cancer cell migration and evasion." (PMID 41149482, 2025). "CKAP4′s role is pivotal in the carcinogenesis of GI malignancies promoting cancer proliferation through various mechanistic pathways." (PMID 41149482, 2025). "Knockdown of either DKK1 or CKAP4 results in impaired Akt activity and colon cancer formation in cancer cells resistant to oxaliplatin." (PMID 41149482, 2025). "CKAP4′s impact on tumor microenvironment and immune evasion is elucidated, offering a new perspective on its contribution to cancer progression." (PMID 41149482, 2025). "CKAP4 and LRP6 have been reported to be direct DKK1 receptors implicated in cancer cell proliferation, with similar affinities but distinct cysteine-rich domains." (PMID 38529014, 2024).